LAMP1 (lysosome associated membrane protein 1)
Diseases named in the same sentence as LAMP1 in open-access papers (continued):
Sharing a sentence is not in itself a finding about the gene and the disease.
tumor (continued). "Additionally, LAMP1 was identified as a direct target responsible for UBL4A-induced tumor suppression and autophagy inhibition." (PMID 39669571, 2024). "A comprehensive analysis of the RNA sequencing data from 539 ccRCC patients and 72 normal tissues sourced from the TCGA database revealed a significant decrease in LAMP1 mRNA expression within tumor tissues, both in unpaired samples (n = 611) and paired samples (n = 72) (P<0.001)." (PMID 39669571, 2024). "In addition, the number of LC3 and LAMP-1 co-localized cells also decreased in CHI3L1-KO tumor tissues." (PMID 37340009, 2023). "Additionally, analysis of LAMP1 immunoreactivity in each TMA via a density heatmap identified areas of dense immunoreactivity for LAMP1 that mostly coincided with tumor-stromal borders and areas of pleomorphism." (PMID 36127469, 2022). "Protein analysis of tumor samples excised from mice has further demonstrated that SDS-203 significantly enhanced the lysosomal marker protein LAMP1, indicating the role of SDS-203 mediated lysosomal upregulation in tumor regression without affecting the overall health of the mice." (PMID 35322026, 2022). "Furthermore, overexpression of NUPR1 in tumor cells significantly increased the distribution of AhR to lysosome marker LAMP1." (PMID 36258210, 2022). "A different degree of LAMP1 content was detected among MCs of the tumor microenvironment." (PMID 36012196, 2022). "Due to the dense-diffuse and vesicular expression pattern of E-cadherin already described in high-magnification images, LAMP1 and Giantin vesicles showed a high degree of overlapping with E-cadherin (0.756 ± 0.069% and 0.797 ± 0.087%, respectively) in tumor tissue." (PMID 35203558, 2022). "E-cadherin overlapping with the lysosomal system, as detected with the LAMP1 marker, recorded a more prominent drop in tumor tissues, with a statistically significant difference from control gastric areas, and this drop even accentuated for higher grade tumors." (PMID 35203558, 2022). "As a result, the tumour volume and weight were sharply diminished via circ‐LAMP1 absence." (PMID 33675150, 2021). "Interestingly, two patients who initially responded to TKI demonstrated a change in the LAMP1 distribution at the time of progression of the disease, when the tumor stopped responding to EGFR TKI." (PMID 32194831, 2020). "They demonstrated that when miR‐23a and TGF‐β were delivered by microvesicles isolated from hypoxic IGR‐Heu, K562 and T1 tumour cells into MK‐92 cells, then the expression of CD107a/LAMP1 was reduced and the number of NKG2D activator surface receptors was decreased in these cells." (PMID 33169503, 2020). "Finally, LAMP1 is expressed at the cell surface of tumor cells, and has been shown to play a role in cell-adhesion and tumor progression." (PMID 32673351, 2020). "In response to stimulation with Vγ9Vδ2 T cell pAgs, these CD56+ effector Vγ9Vδ2 T cells upregulated surface expression of lysosomal-associated membrane protein 1 (LAMP-1, also known as CD107a) and exhibited strong cytotoxicity against MOLT-4 tumour cells in vitro." (PMID 32235722, 2020). "HumAb1 conjugated to DM4 maytansinoid derivative showed anti-tumor efficacy in pre-clinical studies when administered to mice bearing cell surface LAMP1 positive patient-derived tumors." (PMID 32673351, 2020). "In addition, we demonstrate that LAMP1 is a direct target in UBL4A-induced tumor suppression and inhibition of autophagy." (PMID 31288830, 2019). "These and other data suggest that LAMP1 is involved in tumor progression, metastasis and invasion." (PMID 30344951, 2018). "In addition, the transcription of LAMP1 increases with the degree of cancer advancement, implying that its mRNA levels correlate with malignant tumor transformation." (PMID 30344951, 2018). "Additionally, staining of tumor sections for cholesterol and LAMP-1 showed lysosomal cholesterol accumulations as expected by our in vitro results." (PMID 28036299, 2017).
tumor (continued). "Currently, it is believed that LAMP1 is partly responsible for maintaining lysosomal integrity and function, and plasma membrane expression of LAMP1 may play a role in tumor cell differentiation and metastasis." (PMID 27727322, 2016). "The cell surface-expressed portion of LAMP1 maybe serve as a ligand for galectin 3, mediating cell-cell adhesion and indirectly tumor spread." (PMID 20831833, 2010). "Moreover, there was noticeable increase in T cell infiltration/LAMP-1 staining between day 5 and 16 which corresponded well with the observed decrease in tumor size." (PMID 21179470, 2010). "Additionally, we observed lower tumor uptake in Caco-2 xenografts compared to MDA-MB-231 models, which may reflect differences in LAMP1 expression levels, tumor vascularization, or antibody penetration between these cancer types." (PMID 40872517, 2025). "Furthermore, it is suggested that the tumor-suppressive role of LAMP1 may be mediated by LC3C-induced autophagy." (PMID 39669571, 2024). "Notably, LAMP1 exhibits diverse functions across different tumor types." (PMID 39669571, 2024). "However, L-NMMA, SC, or both compounds did not affect idNK activity towards K562 tumor cells or the expression of lysosomal-associated membrane protein-1 (LAMP-1; CD107a) in our research." (PMID 34768607, 2021). "We focused on LAMP1 because of its involvement in lysosomal exocytosis, in movement of lysosomes along microtubules, and in the fusion of phagosomes with lysosomes; it may also play a role in tumor cell metastasis." (PMID 31288830, 2019). "Moreover, LAMP1 is highly active in the membranes of aggressively metastatic tumor cells." (PMID 30344951, 2018). "Utilizing an anti-LAMP1 mAb PET tracer, we observed significant tumor uptake as early as 24 h post-injection, with tracer accumulation and retention persisting for up to 7 days." (PMID 40872517, 2025). "Therefore, upregulation of LAMP1 in these contexts may serve as a marker for increased MDSC activity and a more aggressive tumor phenotype, suggesting that targeting LAMP-1 could be a potential therapeutic strategy to disrupt the immunosuppressive network established by MDSCs." (PMID 40872517, 2025). "Given the strong relation of LAMP1 with tumor growth, invasion, aggressiveness, as well as an immunosuppressive TME, LAMP1 PET imaging should be further investigated as a prognostic biomarker." (PMID 40872517, 2025). "To accomplish this, we performed LAMP1 and CD63 immunostaining on tumor biopsies collected from the same patients before and after treatment." (PMID 39930269, 2025). "Co-cultivation with K562 cells induced a marked increase in LAMP-1 expression on untreated NKL cells, confirming activation of NK cell cytotoxic degranulation upon exposure to tumor cells." (PMID 38318189, 2024). "Immunohistochemistry revealed that the LC3 and LAMP1 expression increased, but the mTOR and MET expression decreased in IL-32γ-overexpressing mouse tumor tissues." (PMID 39519229, 2024). "Immunohistochemical staining of ESCC patients indicated that LAMP1 expression level was significantly different between TNM stage and tumor histological differentiation degree." (PMID 37091857, 2023). "NK cell cytotoxicity was determined by staining a marker of cytotoxic degranulation LAMP-1 and by the intracellular IFN-γ staining after 4 h, and the percentage of killed K562 tumor cells (DiD+DAPI+) was determined after 6 h by flow cytometry." (PMID 36300122, 2022). "Specifically, miR-23a was enriched in hypoxic tumor exosomes, leading to the inhibition of the NK cell degranulation, evidenced by the reduced LAMP-1 (CD107a) expression." (PMID 36248881, 2022). "Previous studies have reported the important role of CD107a (LAMP1) in cytolytic activity of immune cells such as NK and CD8+ T cells when encountering tumor cells." (PMID 34072864, 2021).
tumor (continued). "Inhibition of circ-LAMP1 decreased cell proliferation and invasion of CCA cell lines in vitro, as well as CCA tumor growth in xenograft mouse models, indicating the potentials of circ-LAMP1 as a biomarker and therapeutic target of CCA." (PMID 34282753, 2021). "Another example of the consequences of deregulated lysosomal exocytosis is that redistribution of LAMP1 and LAMP2 at the PM of cancer cells promotes tumor invasion and metastasis via the interaction of their glycan exposed domains with galectins and selectins." (PMID 33718382, 2021). "Our tissue IHC staining data demonstrate that LAMP1 and LAMP2 expression is highly positive at the apical site of tumor cells." (PMID 31425520, 2019). "However, LAMP1 expression levels were similar between CD45+ and CD45− populations in the tumor (81.8% vs. 79.67%, respectively)." (PMID 40872517, 2025). "We used LAMP1 detection to distinguish NK cells poised to rapidly degranulate from non-responsive NK cells upon tumor cell challenge." (PMID 40155684, 2025). "Reduction in the expression of IFN-γ, granzyme B, TNF, CD107a (also termed LAMP-1, a marker of degranulation in NK and CD8+ T cells), CD16-dependent antibody-dependent cell-mediated cytotoxicity (ADCC), or reduced tumor cell killing, are the hallmarks of “dysfunctional” NK cells." (PMID 39768300, 2024). "LAMP1 expression in NK cells—a potential marker of anti-tumor activity—was consistently high, independent of CIITA expression in U87 or GM2." (PMID 38201622, 2023). "We first tested the cell-surface induction of CD107a (LAMP1) in all patients, which reflects NK-cell degranulation capacity when triggered by the prototypical K562 tumor cell line or antibody-coated target cells (referred to as antibody-dependent cell cytotoxicity [ADCC] conditions thereafter)." (PMID 23236375, 2012). "To explore this hypothesis, we investigated the small percentage of LAMP1+ NK cells occurring in the absence of stimulation with tumor cells." (PMID 40155684, 2025). "Administration of RIP‐12 inhibited the growth of IMR‐32 cell‐derived xenograft tumors, as evidenced by reduction in tumor volume, weight, and Ki‐67 proliferative activity, along with up‐regulation of NR1D1, RIOK3, FLCN, or FNIP1 as well as down‐regulation of LAMP1." (PMID 40899609, 2025). "Furthermore, IGN523 has been shown to trigger caspase‐3 and caspase‐7‐mediated apoptosis in tumor cells, while also enhancing lysosomal penetration into tumors by forming a complex with CD98 and anchoring with LAMP‐1 (for more details about clinical trial of this section)." (PMID 40959206, 2025). "In our study, we demonstrated that NDV infection causes post-transcriptional degradation of both LAMP1 and LAMP2 proteins in various tumor and avian cells, while it does not significantly affect the expression of other lysosomal membrane proteins including LAMP3, LIMP II, and LAPTM5." (PMID 38354122, 2024). "Of note, substance p stimulation induced a LAMP-1 translocation almost 10-fold higher than that induced by the aggressive tumor cells, perhaps suggesting that massive degranulation is not a dominant mechanism of MCs activation in the tumor stroma." (PMID 32722549, 2020). "The humoral and cellular immune responses were poor, and no tumor protection was obtained; but, when the HPV E7 gene was fused to the secretory Sig protein and lysosome-associated membrane protein 1 (LAMP-1), enhanced E7‐specific CD4+ helper T-cell and CD8+ cytotoxic T-cell activity was observed." (PMID 24937089, 2014). "Importantly, when we analysed CD107a (LAMP-1), which is a sensitive marker of NK cell degranulation/cytotoxic activity, we observed significantly higher (P<0.001) levels of CD107+ NK cells in pEEVGmCSF-b7.1-treated groups when compared with untreated and pEEV control tumours." (PMID 25373914, 2015).
tumor (continued). "Furthermore, the expression levels of autophagy-related markers (LC3 and LAMP1) were more increased in non-tumor tissues than in liver tumor tissues, but the expression levels of mTOR and MET were decreased in non-tumor tissues." (PMID 39519229, 2024). "Therefore, GW4869 decreases release in EVs of syntenin-1 and LAMP1, but not the other proteins, including CD63, and it conversely tends to increase release of larger/heavier EVs, as previously observed in other tumor cells." (PMID 34282141, 2021).
infection (379 papers, 2007 to 2026). The state of being infected such as from the introduction of a foreign agent such as serum, vaccine, antigenic substance or organism. "In microglia, the fraction of Listeria associated with Lamp1 remained close or below 10% over the 24 h course of infection." (PMID 40522474, 2025). "In contrast, NEDD9 clustered and colocalized with ST at 4 hours post infection and with lysosomal-associated membrane protein 1 (LAMP-1)." (PMID 40506423, 2025). "As L. pneumophila enters the replication phase, most infected phagosomes acquire lysosomal characteristics, and by ~18 h post-infection, vacuoles exhibit an acidic pH and endosomal markers such as lysosome-associated membrane protein 1 (LAMP-1)." (PMID 40862159, 2025). "Phagosomes containing parasites become acidic and display lysosomal markers, such as the GTPase Rab7 and LAMP1 (lysosomal associated membrane protein 1), on their membranes within 30 min post infection." (PMID 38674770, 2024). "Wild-type strain infection caused only 24% LAMP1-associated vacuoles, while more than 79% of the phagosomes harboring the dotA− mutant were positively stained with this lysosomal marker." (PMID 38836877, 2024). "Macrophages internalize about 80% of the A. fumigatus conidia, and almost all the conidia are positive for lysosome associated membrane glycoprotein 1 (LAMP1) in the phagosomes at 60 min of infection." (PMID 34983375, 2022). "Further, we show that LI infection is more dependent on the endosomal receptor lysosome-associated membrane protein 1 (LAMP1) for viral entry relative to LIV." (PMID 35730904, 2022). "After 1.5 h post-infection, bacteria were internalized into macrophages and found in lysosome-associated membrane protein-1 (LAMP-1) positive vacuoles." (PMID 33498782, 2021). "The progressive exclusion of LAMP1 from the vacuolar membrane of BCVs (80% loss at 6 - 12 hrs post infection), allows for the capture vesicles from ER exit sites creating a subcellular compartment with neutral pH that is permissive for replication." (PMID 34858868, 2021). "Concomitantly, at late time points during infection (>18 h p.i.), LCVs acidify and acquire late endosomal and lysosomal markers such as lysosomal-associated membrane protein 1 (LAMP-1)." (PMID 33843434, 2021). "The results showed that only 25 and 17% of intracellular GAS was associated with LAMP-1 in untreated cells at 3 and 5 h of infection, respectively." (PMID 32117141, 2020). "Using the UIS4 (up-regulated in infective sporozoites gene 4) protein as a PVM/TVN marker, LAMP1-positive lysosomes/LE were found associated with the PVM/TVN as soon as 6 hours post-infection (hpi)." (PMID 31138850, 2019). "Transient association with the lysosomal marker LAMP-1 is a hallmark of BCV trafficking during the first hours of infection." (PMID 31243080, 2019). "When treated with BDBV223, but not the other mAbs, VLPs were found to be co-localized with the lysosomal-associated membrane protein 1 (LAMP-1) marker of lysosomes as early as 30 min after infection, which was still observed at 60 min." (PMID 30138408, 2018). "Nonetheless, Lamp1 KD cells and wild-type (WT) cells were equally susceptible to infection with MLV pseudoviruses bearing LASV GPC (and encoding luciferase) at all inputs of virus tested." (PMID 29295909, 2018). "The results showed that 53 and 68% of NZ131 and the nga mutant was associated with LAMP-1 after 1 h of infection, and 17 and 48% after 5 h of infection, respectively." (PMID 30123194, 2018). "To test the effects of a complete loss of Lamp1 on LASV entry and infection, we generated Lamp1 knockout (KO) cell lines using clustered regularly interspaced short palindromic repeats with Cas9 (CRISPR/Cas9) gene editing." (PMID 29295909, 2018). "More than 90% of the cells that were positive for nuclear IRF-1 harbored Mav associated with LAMP1+ membranes at all time points measured over the 3 days infection." (PMID 28806745, 2017).